XIAP (X-linked inhibitor of apoptosis)
Diseases named in the same sentence as XIAP in open-access papers (continued):
Sharing a sentence is not in itself a finding about the gene and the disease.
acute promyelocytic leukemia (1 paper, 2022). An aggressive form of acute myeloid leukemia (AML), characterized by arrest of leukocyte differentiation at the promyelocyte stage, due to a specific chromosomal translocation t(15;17) in myeloid cells. "Arsenic trioxide-induced apoptosis is associated with NF-κB suppression-mediated inhibition of Survivin, XIAP, cIAP2, and Bcl-xL expression in the acute promyelocytic leukemia cell line NB-4." (PMID 35955813, 2022).
alcoholic cardiomyopathy (1 paper, 2021). A dilated cardiomyopathy which is associated with consumption of large amounts of alcohol over a period of years. "Instead, in an in vitro model of alcoholic cardiomyopathy, it was demonstrated that miR-186-5p can directly target the X-linked inhibitor of apoptosis (XIAP) gene (involved in apoptosis suppression)." (PMID 33573156, 2021).
bladder tumor (1 paper, 2019). "We establish a new bridge between XIAP overexpression and MMP2 activation in human BC high invasion, and further help us better understand XIAP induction associated with the progression and the aggression of malignant bladder tumor development." (PMID 31811115, 2019).
brain edema (1 paper, 2017). Increased intracellular or extracellular fluid in brain tissue. "Recombinant XIAP preserved the blood-brain barrier, improved the neurological scores and ameliorated brain edema." (PMID 28327595, 2017).
brain glioblastoma (1 paper, 2020). A WHO grade IV malignant astrocytic tumor that arises from the brain, usually the cerebral hemispheres. "Furthermore, it concentration-dependently suppressed the proliferation and induced apoptosis in human brain glioblastoma U87MG cells by activating caspase-3, while downregulating p-Akt, p-Bad, and X-linked inhibitor of apoptosis protein (XIAP)." (PMID 31963204, 2020).
brain injuries (1 paper, 2011). "In addition, our data showing that IGF-IGF1R signaling up-regulates the expression of neuronal cIAP-1 and XIAP during development and following H/I, strongly suggest that cIAP-1 and XIAP are two candidate targets for therapeutic treatment of H/I-induced brain injuries." (PMID 21718528, 2011).
carcinoid tumor (1 paper, 2017). A slow growing neuroendocrine tumor, composed of uniform, round, or polygonal cells having monotonous, centrally located nuclei and small nucleoli, infrequent mitoses, and no necrosis. "High levels of survivin has been associated with the metastatic potential of carcinoid tumors, and both XIAP and survivin have been implicated in inhibiting the apoptotic pathway and conferring chemoresistance in cancer patients." (PMID 29050323, 2017).
cerebral palsy (1 paper, 2019). A group of disorders affecting the development of movement and posture, often accompanied by disturbances of sensation, perception, cognition, and behavior. "This study is performed to investigate the effects of adenovirus-mediated X-linked inhibitor of apoptosis protein (XIAP) overexpressed bone marrow mesenchymal stem cells (BMSCs) on brain injury in rats with cerebral palsy (CP)." (PMID 31660045, 2019).
cervical tumors (1 paper, 2006). "c-IAP2 and XIAP mRNA levels were similar among the samples, cervical tumors had lower c-IAP1 mRNA levels." (PMID 16504151, 2006).
chordoma (1 paper, 2021). Chordomas are rare malignant tumors arising from embryonic remnants of the notochord in axial skeleton. "In particular, the knockdown of DEPDC1B resulted in not only a significant upregulation of Caspase3, sTNF-R1, but also downregulation of Bcl-2, CD40, HSP27, IGF-1sR, XIAP, Livin, Survivin in chordoma cells." (PMID 34330893, 2021).
condyloma acuminatum (1 paper, 2010). "We investigated the levels of telomerase activity, and inhibitor of apoptosis proteins (IAPs) family (c-IAP1, c-IAP2, XIAP) and c-Myc mRNA expression levels in 20 specimens of Bowenoid papulosis and 36 specimens of condyloma acuminatum in anogenital areas." (PMID 20346172, 2010). "In contrast, the expression levels of Bowenoid papulosis indicated that c-IAP1, c-IAP2 and XIAP mRNA were significantly upregulated compared to those in both condyloma acuminatum samples (p < 0.001, p < 0.001, p = 0.022, respectively) and normal skin (p < 0.001, p = 0.002, p = 0.034, respectively)." (PMID 20346172, 2010).
Cryptosporidium infection (1 paper, 2016). "The role of IAPs in the control of cell death in cryptosporidiosis is reinforced by a study showing that XIAP mediated proteasome-dependent inhibition of activated caspase-3 in C. parvum infection." (PMID 26973630, 2016). "Inhibition of host cell apoptosis during Cryptosporidium infection has also been reported to involve the expression of members of the IAP family (inhibitors of apoptosis proteins) such as c-IAP1, c-IAP2, XIAP, and survivin." (PMID 26973630, 2016).
dementia (1 paper, 2018). Loss of intellectual abilities interfering with an individual's social and occupational functions. "Therefore, a decrease on XIAP and Topors would produce an unbalanced apoptosis regulation that should contribute to the neuronal death observed in the brain of AD and other dementia patients." (PMID 29541381, 2018). "We identified altered proteins in AD not common to other dementias like the E3 ubiquitin-protein ligase TOPORS, Layilin and MICB, and validated the association to AD of the previously controverted proteins DDIT3 and the E3 ubiquitin-protein ligase XIAP." (PMID 29541381, 2018).
dilated cardiomyopathy (1 paper, 2015). Cardiomyopathy which is characterized by dilation and contractile dysfunction of the left and right ventricles. "This suggests that XIAP is a potential therapeutic target of dilated cardiomyopathy in DMD patients." (PMID 25791035, 2015).
ductal carcinomas (1 paper, 2011). "Whereas, Jaffer and his colleagues found a possible role of XIAP in the more aggressive clinical behavior of grade 3, compared with lower-grade ductal carcinomas." (PMID 21645409, 2011).
EBV infection (1 paper, 2025). "IFN-γ–producing NK cells can block EBV-mediated B cell transformation, and we found that XIAP-deficient B cells are exquisitely sensitive to IFN-γ following EBV infection." (PMID 40674368, 2025). "In addition to apoptosis, other forms of programmed cell death may contribute to the increased susceptibility of XIAP-deficient B cells following EBV infection." (PMID 40674368, 2025). "To explore the mechanism by which XIAP supports EBV, but not CD40L/IL-21–driven B cell outgrowth, we tested the effects of XIAP depletion on growth versus survival at early times after EBV infection." (PMID 40674368, 2025). "However, we note that caspase or BAX inhibition rescued proliferation of EBV-infected XIAP-deficient cells, suggesting that apoptosis is major programmed cell death pathway activated at early timepoints of EBV infection in the absence of XIAP." (PMID 40674368, 2025). "In support, caspase 3 and 7 activity was significantly elevated in XIAP-edited B cells or in XLP-2 B cells on day 4 after EBV infection, but not at the same timepoint of CD40L/IL-21 stimulation." (PMID 40674368, 2025). "XIAP editing did not significantly alter EBV infection efficiency, as judged by an EBV genomic GFP reporter that can be used to mark infected B cells." (PMID 40674368, 2025).
esophageal adenocarcinoma (1 paper, 2019). A malignant tumor with glandular differentiation arising predominantly from Barrett mucosa in the lower third of the esophagus. "In the present study, we analyzed the protein expression of XIAP in a large and well characterized collective of esophageal adenocarcinomas." (PMID 31151416, 2019).
Failure to thrive (1 paper, 2023). Failure to thrive (FTT) refers to a child whose physical growth is substantially below the norm. "When a XIAP deficiency patient shows recurrent and severe abdominal pain, failure to thrive, GI bleeding, and diarrhea, it is reasonable to suspect an IBD and perform a GI endoscopy." (PMID 36675441, 2023).
glaucoma (1 paper, 2022). Increased pressure in the eyeball due to obstruction of the outflow of aqueous humor. "In addition, we also quantitatively analyzed both groups for the expression of apoptosis-related (BAD, BAX, BCL2L10, and XIAP) and autophagy-associated (HAX1 and Beclin-1) marker proteins, since both signaling cascades are supposed to be highly involved in the molecular pathogenesis of glaucoma." (PMID 36313990, 2022).
HCMV infection (1 paper, 2021). "Akt activated by HCMV infection leads to the upregulation of a unique subset of anti-apoptotic proteins, including myeloid cell leukemia-1 (Mcl-1) protein, heat shock protein 27 (HSP27), and X-linked inhibitor of apoptosis (XIAP), necessary for the survival of infected monocytes." (PMID 34663377, 2021).
hearing loss (1 paper, 2014). "Because XIAP expression was low during the neomycin-sensitive period, we overexpressed XIAP in mice and found that it could protect against neomycin-induced hearing loss at low frequencies and HC loss in the apical turn of the cochlea." (PMID 25278835, 2014).
Hepatic steatosis (1 paper, 2019). Steatosis is a term used to denote lipid accumulation within hepatocytes. "Furthermore, mice fed an HFD had increased AST, ALT, and AKP levels and serum endotoxin content, suggesting that an HFD promoted hepatic steatosis in these mice and may be associated with differential regulation of XIAP." (PMID 31841118, 2019). "The detrimental effects of XIAP blocking on hepatic steatosis and related pathologies were also confirmed in PA-treated mouse liver cells." (PMID 31841118, 2019). "Taken together, the present study helped to elucidate how HFD-induced hepatic steatosis was regulated by XIAP, possibly via the inhibition of NLRP3 signaling and oxidative stress injury." (PMID 31841118, 2019). "In order to elucidate the role of XIAP in hepatic steatosis and its complications, XIAP knockdown mice were generated by in vivo siRNA transfection and then fed an HFD for 12 weeks." (PMID 31841118, 2019). "Therefore, XIAP is a potential therapeutic target for HFD-induced liver steatosis and related systemic metabolic diseases." (PMID 31841118, 2019). "In contrast, overexpression of XIAP by transfection in vitro restrained PA-stimulated hepatic steatosis by suppression of oxidative stress, NLRP3 related inflammatory response, and impairment of Nrf2 activity, further alleviating abnormal metabolic disorder associated NAFLD." (PMID 31841118, 2019). "XIAP suppresses the assembly of NLRP3 inflammasomes by negatively regulating NLRP3 signaling, reducing the formation and release of inflammatory cytokines, and moderating hepatic steatosis." (PMID 31841118, 2019).
hepatoblastoma (1 paper, 2021). Hepatoblastoma (HB) is a malignant hepatic tumor and is the most common pediatric liver cancer. "We utilized in vitro techniques using a widely used hepatoblastoma-derived tumoral hepatocyte cell line, HepG2, to understand the role of XIAP in alcohol-induced injury." (PMID 34025452, 2021).
Hodgkins lymphoma (1 paper, 2015). A heterogeneous group of malignant lymphoid neoplasms of B-cell origin characterized histologically by the presence of Hodgkin and Reed-Sternberg (HRS) cells in the vast majority of cases. "Hodgkins and Reed Sternberg cells and Hodgkin lymphoma derived B cells involved in this disease express high levels of XIAP." (PMID 26071313, 2015).
infarction (1 paper, 2019). A localised pathological necrosis of tissue resulting from obstruction of the blood supply usually by a thrombus, an embolus, or vascular torsion. "In some ways, overexpression of XIAP could decrease both myocardial apoptosis and infarction under I/R condition, which attributed to the ability of XIAP to inhibit Caspase-3." (PMID 31205587, 2019).
infertile (1 paper, 2014). "In women with tubal factor infertility the high level of mRNAs expression of both anti-apoptotic (XIAP and HSP27) and pro-apoptotic (PTEN) factors was noted comparing to that in the fertile control." (PMID 35761716, 2014). "In women with tubal factor of infertility the increased levels of the expression of mRNAs of pro-apoptotic factor PTEN and also of anti-apoptotic factors XIAP and HSP27 were noted comparing to that in healthy women (P<0.05 in all cases)." (PMID 35761716, 2014).
inflammatory skin disease (1 paper, 2025). Inflammatory skin disorders covers a broad category that includes many conditions ranging in severity, from mild itching to grave medical health complications These disorders are common in people of all ages and races. "Similarly, the genetic deletion of inhibitors of apoptosis proteins (IAPs), including cIAP1, cIAP2, and xIAP, has been associated with the development of inflammatory skin diseases in mice." (PMID 40564127, 2025).
influenza (1 paper, 2016). An acute viral infection of the respiratory tract, occurring in isolated cases, in epidemics, or in pandemics; it is caused by serologically different strains of viruses (influenzaviruses) designated A, B, and C, has a 3-day incubation period, and usually lasts for 3 to 10 days. "In fact, when comparing with influenza B strain, influenza A strain infection markedly increased the levels of the NF-κB downstream survival targets, including Bcl-XL and XIAP." (PMID 27042352, 2016).
intervertebral disc degeneration (1 paper, 2021). "In a study of intervertebral disc degeneration, circVMA21 was found to act as a sponge of miR-200c to regulate X-linked inhibitor-of-apoptosis protein (XIAP) and affected cell apoptosis and the imbalance of extracellular matrix anabolism and catabolism." (PMID 34611269, 2021).
Klinefelter syndrome (1 paper, 2019). A sex chromosome disorder caused by the presence of an extra X chromosome in the male karyotype. "In a study on a large population of Klinefelter syndrome individuals, XIAP was identified among the few ChrX overexpressed genes." (PMID 30871455, 2019).
lipid metabolism disorder (1 paper, 2025). "SNHG4 overexpression mitigated the lipid metabolism disorder and inflammation triggered by FFA, while this effect was suppressed by silencing XIAP." (PMID 41084767, 2025).
liposarcoma (1 paper, 2022). A usually painless malignant tumor that arises from adipose tissue. "Here we report that tetrandrine at 10 μM has strong anti-proliferative, anti-survival, and pro-apoptotic effects on SW872 human malignant undifferentiated liposarcoma cells by controlling the intrinsic caspase pathway, XIAP, STAT-3, and ER stress." (PMID 35740967, 2022).
Lymphatic Metastasis (1 paper, 2019). Transfer of a neoplasm from its primary site to lymph nodes or to distant parts of the body by way of the lymphatic system. "In univariate analysis, lymphatic metastasis and XIAP expression showed a significant association with poor overall survival (p = 0.001 and p = 0.005 respectively)." (PMID 31548877, 2019).
malignant glioma (1 paper, 2023). A grade III or grade IV glioma arising from the central nervous system. "It is is an inhibitor of XIAP and can also act as a mitochondrial targeting agent, which renders it as a promising therapeutic agent against malignant glioma." (PMID 37047552, 2023).
metabolic syndrome (1 paper, 2019). A cluster of metabolic risk factors for CARDIOVASCULAR DISEASES and TYPE 2 DIABETES MELLITUS. "Consistent with previous studies, cells overexpressing XIAP had a reduction in NLRP3 signaling activation, and inflammation-associated dyslipidemia induced by PA treatment was eliminated in these cells." (PMID 31841118, 2019). "The current study indicated that fat-rich diet-induced NAFLD exhibited lower XIAP and Nrf2 activity levels, then mediated an increase in NLRP3 inflammasomes, resulting in hepatic inflammation and dyslipidemia." (PMID 31841118, 2019).
metastasis (1 paper, 2022). The spread or migration of cancer cells from one part of the body (where they first appeared) to another. "Over-expression of XIAP was found to be associated with older age at diagnosis (p < 0.0001), tall cell variant of PTC (p < 0.0001), extrathyroidal extension (p < 0.0001), larger tumor size (p = 0.0007), lymph node metastasis (p = 0.0023) and advanced stage (p < 0.0001)." (PMID 36578953, 2022).
metastatic tumors (1 paper, 2019). "The number of lung metastatic tumors in mice injected with EC9706 (sh-Ctrl) cells was remarkably increased than sh-XIAP group (p < 0.01)." (PMID 31548877, 2019).
myeloid tumors (1 paper, 2020). "XIAP plays an anti-apoptotic role by inhibition of caspases both in lymphoid and myeloid tumors." (PMID 32062612, 2020).
neuropathy (1 paper, 2025). A disorder affecting the nervous system that manifests with pain, tingling, numbness, and/or muscle weakness. "The XIAP-targeting antisense oligonucleotide AEG35156, when taken up by glial cells or neurons, leads to a reduction in XIAP levels within these cells, which can result in peripheral chemotherapy-induced neuropathy in patients." (PMID 40675967, 2025).
Opportunistic infection (1 paper, 2024). An infection that is caused by a pathogen that would generally not be able to cause an infection in a host with a normal immune system. "In conclusion, this case highlights the complex and potentially life-threatening nature of XIAP deficiency, particularly when complicated by an immunosuppressed state, leading to opportunistic infections." (PMID 38912075, 2024).
oral squamous cell carcinoma (1 paper, 2021). "Quercetin promotes cisplatin-induced apoptosis in oral squamous cell carcinoma by reducing the nuclear factor κB (NF-κB) and x-linked inhibitor of apoptosis (xIAP) protein levels and results in the significant inhibition of tumor growth." (PMID 34512232, 2021).
perianal Crohn disease (1 paper, 2023). A Crohn disease involving a pathogenic inflammatory response in the anal region. "Hyperinflammatory conditions, such as X-linked inhibitor of apoptosis (XIAP), often present with a severe perianal Crohn’s disease phenotype." (PMID 36986830, 2023).
periodontitis (1 paper, 2024). An acute or chronic inflammatory process that affects the tissues that surround and support the teeth. "In periodontitis, survivin and XIAP prolong the lifespan of inflammatory cells." (PMID 39493178, 2024).
Peutz-Jeghers syndrome (1 paper, 2025). An autosomal dominant disorder caused by pathogenic variants in the STK11 gene, characterized by hamartomatous polyps in the gastrointestinal tract, mucocutaneous pigmentation and increased risk of GI and extra-GI malignancies. "Both WT and kinase-inactive LKB1 antagonized XIAP to restore apoptosis, but somatic mutants of LKB1 found in Peutz-Jeghers syndrome (PJS) failed to do so." (PMID 40544190, 2025).
premature ovarian failure (1 paper, 2017). "In plasma of premature ovarian failure (POF) patients, miR-23a has been found to decrease X-linked inhibitor of apoptosis protein (XIAP) expression (at the mRNA and protein levels) with a simultaneous increase of cleaved caspase-3 protein, thereby increasing apoptosis in GCs." (PMID 28208755, 2017).
presbycusis (1 paper, 2014). Bilateral hearing loss caused by progressive degeneration of cochlear structures and central auditory pathways, typically associated with the aging process. "The same ubiquitous XIAP overexpression mice used in this study also exhibit later onset of presbycusis and an insensitivity to noise-induced hearing loss." (PMID 25278835, 2014).